SNORD18C (small nucleolar RNA, C/D box 18C)
Synonyms: U18C
Gene: Small nucleolar RNA gene on chromosome 15 (66,501,250 to 66,501,318, reverse strand). Ensembl gene ENSG00000199574.
Gene Ontology:
Biological process: RNA processing
Cellular component: nucleolus
Homologues: Orthologues: chimpanzee SNORD18 (99% identical), macaque SNORD18 (97% identical), pig SNORD18 (90% identical), rat Snord18c (88% identical), dog SNORD18 (87% identical), mouse Gm22455 (86% identical), tropical clawed frog SNORD18 (83% identical). Paralogues in human: SNORD18B (88% identical), SNORD18 (87% identical), SNORD18 (84% identical), SNORD18A (78% identical).